PCOTH (prostate and testis expressed opposite C1QTNF9B and MIPEP)
Description:
May be involved in growth and survival of prostate cancer cells through the TAF-Ibeta pathway.
Synonyms: C1QTNF9B-AS1
Gene: Long non-coding RNA gene on chromosome 13 (23,888,749 to 23,897,263, forward strand). Ensembl gene ENSG00000205861.
Subcellular location: Cytoplasm
Diseases named in the same sentence as PCOTH in open-access papers:
PCOTH is named in the same sentence as 1 disease in open-access papers, as found by Europe PMC text mining. Sharing a sentence is not in itself a finding about the gene and the disease.
PCOTH shares sentences with these, for which no sentence is quoted: prostate carcinoma (1 paper).